IGF2 (insulin like growth factor 2)
Diseases named in the same sentence as IGF2 in open-access papers (continued):
Sharing a sentence is not in itself a finding about the gene and the disease.
tumor (continued). "A heat map of gene expression levels in tumors, ordered in descending order, on the basis of the phosphorylated IGF1R signal, provided a visualization of the expression profile of IGF pathway genes in each tumor, and highlighted the mutually exclusive nature of IGF1 and IGF2 expression." (PMID 28882129, 2017). "The differences between the groups were not statistically significant, and moreover, several tumor samples with increased copy numbers exhibited low IGF2 mRNA and, vice versa, several samples with decreased copy numbers possessed high levels of IGF2 mRNA." (PMID 29017567, 2017). "This expanded model incorporated the IGF2 axis of the IGF network (i.e., IGF2 and IGF2R) and was used to assess the hypothesized roles of IGF2R and IGFBPs as tumor suppressors." (PMID 26861122, 2016). "In HCC, miRNA-216b could function as a tumor suppressor by targeting IGF2BP2 and subsequently suppressing the downstream IGF2." (PMID 26989293, 2016). "The mitogenic effect of IGF2 overexpression suggests a role in tumor maintenance rather than initiation, which would rather be triggered by other actors, such as WNT pathway." (PMID 27471492, 2016). "Previous studies have suggested that ZKSCAN3 directly or indirectly regulates the expression of various genes, such as CCND1, CCND2, EGFR, IGF-2, integrin-β4, NF-κB, and VEGF, all of which are known to involve tumorigenesis, tumor progression, and/or metastasis." (PMID 27447553, 2016). "No IGF-1 or IGF-2 expression was found in the cell lines (data not shown), confirming the paracrine activation of the pathway in this tumor." (PMID 25906745, 2015). "We demonstrate that IGF2 expression in IH is strongly related to the expression of a cancer testes and suspected oncogene BORIS (paralog of CTCF), placing IH in the unique category of being the first known benign BORIS positive tumor." (PMID 26496499, 2015). "In this study, expression levels of IGF-1, IGF-2, and their receptors were determined in paired samples of tumor and adjacent non-neoplastic liver from patients who underwent liver resection for HCC." (PMID 25052889, 2014). "For reasons not clear, there are several neoplasms noted to have high levels of IGF-2 mRNA without exhibiting elevated hormone activity." (PMID 24934576, 2014). "Therapy with MEK inhibitor U0126 produces only a transient inhibition of tumor glycolytic activity but does not inhibit tumor growth, which is due to continuing IGF2-induced signaling from IGF1R through the PI3K-AKT-mTOR pathway." (PMID 22875335, 2013). "Therapy with MEK inhibitor U0126 produces only a transient inhibition of tumor glycolytic activity but does not inhibit tumor growth, which is most likely due to continuing IGF2-induced signaling from IGF1R through the PI3K-AKT-mTOR pathway." (PMID 22875335, 2013). "This confirmed that Igf2 was expressed at asignificantly higher level in tumours with one or more insertions in a networkCIS gene, than in tumours with no insertion in a network CIS gene (p<0.0001)." (PMID 24252690, 2013). "Our analysis shows that despite overexpression levels ranging from 7 (basal) to 87 (ACTH-induced) fold, Igf2 has no tumour initiating potential in the adrenal cortex." (PMID 22952916, 2012). "Indeed, in tumor tissue from both control and MKR+/+ mice we observed barely detectable levels of Igf2 mRNA expression." (PMID 22226054, 2012). "In the tumor group, IGF-1 and IGF-2 levels were strongly correlated with ERα expression (r = 0.6439 for IGF-1, r = 0.5228 for IGF-2), and were weakly correlated with ERβ expression (r = 0.4155 for IGF-1, r = 0.3555 for IGF-2)." (PMID 22720981, 2012).
tumor (continued). "Altogether, these experiments suggested that there was no major acceleration of tumour development upon overexpression of Igf2 in the context of constitutive β-catenin activation in 10 month-old adrenals." (PMID 22952916, 2012). "In our study, the IGF-1 and IGF-2 mRNA levels are much higher in tumor cells and tumor-adjacent cells than those in control tissues, suggesting that IGF-1 and IGF-2 may be a critical mediator for transforming from normal cell into tumor cells." (PMID 22720981, 2012). "Increased IGF2 in patients with PCa appears to be the result of impaired imprinting in non-neoplastic cells rather than a paracrine tumor product." (PMID 23781309, 2012). "Surprisingly, the same transgenic mice do not show tumour development in the mammary epithelium, despite a 50 to 100-fold increase in IGF2 expression in their mammary glands and an inhibition of apoptosis during involution." (PMID 22952916, 2012). "GPC3 modulates the effect of growth factors such as IGF-2, BMP-7 and FGF-2 on hepatoma cells and may recruit M2 tumor-promoting macrophages to the HCC microenvironment." (PMID 22564378, 2012). "Furthermore, the addition of both IGF-1 and IGF-2 to the PLC HCC cell line induced increased cell proliferation in a dose dependent manner, showing that the major tumor promoting effects of IGF ligands on HCC are exerted through IGF-1R." (PMID 21729319, 2011). "While the expression of IGF-2 was slightly different between tumor grades, this was not statistical significant (P = 0.093)." (PMID 20178612, 2010). "The LOI positive rate of the LIT1, IGF2 and H19 was higher in patients with advanced tumour stage than with early stage, but the difference was not statistically significant (p = 1.000)." (PMID 19737423, 2009). "High frequency of IGF2 LOI was observed in tumor and adjacent normal tissues and Igf2 LOI with Apc+/Min mice showed a shift toward less differentiation and an increase in tumor initiation indicating that IGF2 LOI occur at an early stage in cancer development." (PMID 19737423, 2009). "Furthermore, very low expression levels of H19 mRNAs and substantial expression levels of IGF2 mRNAs in HB tumours with UPD or LOI, and substantial expression levels of both IGF2 and H19 mRNA in HB tumours with ROI were found." (PMID 19034281, 2008). "PLAG1 positively regulates IGF2, and its expression was detected in 12 tumours, foetal liver RNA and 2 cell lines, but not in 8 tumour and 3 normal liver tissues." (PMID 19034281, 2008). "Taken together, these results suggest IGF2 can promote tumor growth, in part through direct or indirect myeloid cell polarization, which is supported by IGF2 receptor expression in myeloid cells in the TME and high IGF2 expression in a subset of human GBM tumors." (PMID 41568176, 2026). "Tumour epithelial cells were further reclustered into two distinct subclusters (Subcluster 1 and Subcluster 2), and DUSP9 was predominantly expressed in Subcluster 1, which was enriched with other oncofetal and stemness‐related genes such as AFP, GPC3, IGF2, ANPEP and EPCAM." (PMID 41383134, 2025). "We can hypothesize that IR, expressed as the mitogenic IRA isoform in these tumours, coupled with the overexpression of IGF2 in ACC, but not in ACA, can sustain the growth of ACC cells more than IGF1R." (PMID 40038716, 2025). "Our previous findings also showed a substantial upregulation of IGFBP3 in both α-SMA-expressing stromal cells and tumor cells; unfortunately, expression levels of IGF2 could not be evaluated in that study as it was not included within the analysis panel." (PMID 40522948, 2025). "As a result, we hypothesize the laboratory assay may not appropriately detect high molecular weight IGF-2 that is most commonly expressed by tumor cells." (PMID 40727482, 2025). "This suggests that radiotherapy may induce tumor cell death and suppress IGF-2 secretion without requiring significant tumor shrinkage, as evidenced by stable tumor dimensions on follow-up CT." (PMID 41367853, 2025).
tumor (continued). "Additionally, a comprehensive analysis using the tumor immune dysfunction and exclusion (TIDE) system was conducted on 4,028 tumor samples from 9 cancer types of TCGA database, indicating significantly higher IGF2 expression in the immune-excluded tumors." (PMID 39545420, 2024). "Importantly, IGF2 inhibition impeded the formation of an immunosuppressive TME and enhanced the recruitment of antitumor CD8 + cytotoxic T-lymphocytes (CTLs), resulting in markedly improved survival of mice bearing GBM and BCBM tumor." (PMID 38853689, 2024). "In C2 IGF2+ tumor cells, the expression of MDK might have been upregulated, which could promote the activation and transformation of fibroblasts by binding to NCL on fibroblasts, thus forming CAF that support tumor growth and progression." (PMID 39896800, 2024). "The suppression of tumor growth by linsitinib (10 mg/kg) could not be attributed to the inhibition of the IGF1R on tumor cells, as linsitinib did not significantly add to the effect on tumor growth in Igf2-cKO mice." (PMID 39545420, 2024). "Finally, to explain the mechanistic role of DNA methylation changes in WT relapse, we explore the genes controlled by the differentially methylated IGF2 region and show elevated expression of INS-IGF2 transcript in tumor tissue of patients who have relapsed after treatment." (PMID 39593106, 2024). "The lack of consistency between the results from the PBL samples and tumour tissues may reflect the fact that IGF2 methylation is merely a predictive marker rather than a prognostic marker." (PMID 37213278, 2023). "In addition, IGF2 induced by ischemia and hypoxia participates in angiogenesis of human hepatocellular carcinoma, and significantly increases VEGF mRNA and protein levels in tumor tissues in a time-dependent manner." (PMID 37576896, 2023). "Because of intratumour heterogeneity, the detection of a biomarker from a single biopsy or one section of a tumour tissue sample might not necessarily represent the IGF2 methylation status of a given patient." (PMID 37213278, 2023). "CircWHSC1 played a tumor-promoting role in HCC by elevating HOXA1 through sponging miR-142-3p, and circTMEM45A acted as a miR65 sponge to relieve the repressive effect of miR-665 on its target insulin growth factor 2(IGF2), upregulation of IGF2 and HCC progression." (PMID 35530313, 2022). "Moreover, tumor cells did not seem to have enough enzymes to act on pro-IGF-2; thus, the excess pro-IGF-2 competes with IGF-1 and IGF-2 in binding to IGFBP to form a 40–50–kDa binary complex." (PMID 36034453, 2022). "Moreover, we show that blocking IGF2 stimulation activity, using an inhibitor of the IGF1 receptor (IGF1R), enhances isiPI3K efficacy and displays a synergistic anti-tumor effect in vitro and superior anti-tumor activity ex vivo and in vivo." (PMID 34067117, 2021). "Notably, authors proposed that in those HCAs associated with an increase in insulin-like growth factor 2 (IGF2) by inactivation of the insulin-like growth factor 2 receptor (IGF2R) gene, a therapy targeting IGF2 could effectively prevent tumor malignancy." (PMID 33922238, 2021). "Inversely, in IGF2-low model treatment, BI 885578 did not significantly inhibit tumor growth." (PMID 31623387, 2019). "In vivo studies also note that IGF2 tissue expression in CRC correlates with expression of other proliferation markers, e.g., proliferating cell nuclear antigen (PCNA), which confirms the role of this growth factor in tumor cell proliferation through a paracrine mechanism." (PMID 31623387, 2019). "IGF2R also has a high affinity for IGF ligands, particularly IGF2; however, the receptor lacks an intracellular tyrosine kinase domain that is essential for the activation of the IGF pathway, thus, the receptor acts as a “decoy” of the IGF pathway and is recognized as a tumor suppressor gene." (PMID 30373548, 2018). "IGF2 expression was increased in tumor and adjacent background, nontumor tissue." (PMID 29702590, 2018).
tumor (continued). "Therefore, to investigate IGF1R as a mediator of IGF2 survival signaling, and as an potential therapeutic target in MRT, we determined whether blocking IGF1R inhibited tumor cell growth in vitro." (PMID 28521298, 2017). "Albeit we found IGF-2 to have a higher expression in tumor vs. diploid fibroblasts we did not observe any major alteration in IGF-2 expression levels after treatment with compounds (data not shown) making this hypothesis unlikely." (PMID 27384680, 2016). "Several reports showed the involvement of stimulation of IR by insulin or IGF-2 in cancer cell progression suggesting that IGF-1R and IR both are therapeutic targets and inhibition of both receptors may be required for optimal tumor growth inhibition." (PMID 27127884, 2016). "However, methylation of IGF2 gene in HCC tumor tissues was not significantly higher than neither adjacent tissues nor normal tissues, revealing that methylation of IGF2 gene didn't play a significant role during the hepatocarcinogenesis process." (PMID 27835605, 2016). "In summary, our study suggests that in patients with HCC, miR-216b, which could be transcriptionally reduced by HBx, functions as a tumor suppressor by targeting IGF2BP2 and subsequently suppressing the downstream IGF2, AKT/mTOR and MAPK/ERK signaling pathways." (PMID 25741595, 2015). "Indeed, Igf2 isa direct target gene of the transcription factor PLAG1, which plays an important role in the tumorigenic process, since genetic ablation of Igf2 in the PLAG1 transgenic mouse model significantly delayed the tumor formation." (PMID 26167473, 2015). "It is not known whether IGF2 overexpression is absent at the beginning of tumorigenesis or whether it is lost during the progression of the IGF2-low tumor." (PMID 25089899, 2014). "For example, for tumor types without high IGF2, increased IR-A/IR-B mRNA ratio may be of benefit to the patients due to the lack of proliferation signaling through IR-A." (PMID 24571613, 2014). "Interestingly, we observed a shorter latency of tumor formation - 10.4 weeks (range: 7–25 weeks) but a similar incidence as 14 of 44 p16/p19−/−×BKE mice (32%) developed tumors in the left hindimb when injected with DF-1 cells expressing KrasG12D and Igf2." (PMID 24733554, 2014). "In all patients, IGF-2 expression was upregulated in tumor and adjacent non-neoplastic liver." (PMID 25052889, 2014). "Collectively, our data show that IGF2 overexpression in the context of constitutive Wnt/β-catenin activation results in a moderate acceleration of tumour development but that it is not sufficient to trigger malignant tumour progression." (PMID 22952916, 2012). "However, ACTH also had an intrinsic effect on tumour progression in ΔCat adrenals even though Igf2 expression levels were not increased." (PMID 22952916, 2012). "Altogether, these data strongly suggested that Igf2 overexpression alone could not trigger tumour development in the adrenal cortex." (PMID 22952916, 2012). "However, most models of Igf2 overexpression do not develop tumours although they recapitulate developmental overgrowth alterations associated with BWS." (PMID 22952916, 2012). "Unsupervised two-dimensional cluster analysis of the DNA methylation β-values revealed a distinct cluster of 11 tumor samples, the majority of which contained BRAFV600E and showed frequent DNA methylation of known CIMP-associated markers, including CDKN2A, IGF2, and MLH1 (data not shown)." (PMID 20027224, 2009). "Furthermore, our study demonstrates that the IGF1R inhibitor linsitinib, known for its reported inhibition of tumor growth in various cancers, did not augment the inhibitory effect on tumor growth in Igf2-cKO mice and mice with specific fibroblast depletion (iDTRfl/flS100a4CreERT mice)." (PMID 39545420, 2024). "Insulin-like growth factor 2, insulin and glucagon are not involved in GSDME-SG-mediated tumour cell death in vitro; therefore we speculated that exocrine enzymes are involved in GSDME-deficient tumour cell death." (PMID 35292781, 2022).
tumor (continued). "Notably, IGF2 may not have to be produced by the tumor cells themselves, but may instead be secreted by neighboring cells." (PMID 34680217, 2021). "However, the factors influencing IGF2 expression level in tumor cells are not clear." (PMID 34837929, 2021). "Targeting IGF2, which can be secreted by MAFs to support metastatic tumor growth and modulate the TIME, along with its neutralizing antibody xentuzumab can inhibit the growth of MAF-tumor cell xenografts in vivo and may offer a novel therapeutic avenue for metastatic breast cancer." (PMID 34112258, 2021). "Therefore, IGF-2 secretion could have induced mobilization of endothelial progenitor cells and bone marrow derived progenitor cells to the TME, leading to an increased vasculature in cixutumumab-treated xenograft tumours." (PMID 26465273, 2015). "Accordingly, destruction of the H19 and IGF2 expressing tumor cells not only will eliminate part of the tumor but will also diminish the supply of mitogenic IGF2 to neighboring tumor and non-tumor cells and may lead to arrest of tumor growth and prevent following metastases process." (PMID 21162716, 2010). "At surgery, RNAscope in situ hybridization of IGF2 and H19 revealed the presence of 14% of mosaic cells in one FFPE non-tumor slide but not in the frozen sample." (PMID 37932266, 2023). "What is particularly interesting is that these same pathways and genes are upregulated in metastatic pancreatic neuroendocrine tumors, a tumor type that is presumed to have different tumor drivers than ileal NETs (e.g., MEN1 but not IGF2)." (PMID 34680217, 2021). "Immunohistochemical staining revealed that the tumor was positive for signal transducers and activators of transcription 6 (STAT6), CD99, bcl-2, insulin-like growth factor-2 (IGF-II), and CD34, and negative for CD31, EMA, S-100, SMA, and desmin." (PMID 30976927, 2019). "What is striking is the fact that, when considering all tumor samples together without separation in groups, we find a highly significant correlation of KLF4 and IGF2 expression (p < 0.0001, Spearman’s rank correlation coefficient r = 0.668)." (PMID 29017567, 2017). "MTMR7 was lost to a higher percentage in tumor tissues of both patient groups (T2DM: 88%, 15 of 17; IGF2 LOI: 92%, 12 of 13) than in individuals with neither T2DM nor IGF2 LOI (44%, 7 of 16)." (PMID 27409167, 2016). "Although these neoplasms often have elevated levels of IGF-2 mRNA, they do not always produce elevated circulating levels of IGF-2 or big IGF-2." (PMID 24934576, 2014). "Of note, the amount of Igf2 mRNA in AXT cells was found to be very low, and the protein was undetectable (<1.5 ng/ml) in corresponding culture supernatants or tumor homogenates by ELISA (data not shown)." (PMID 23226335, 2012). "Samples where RFLPs were present in the lymphocyte DNA sample but absent or with an altered ratio in the tumor sample were considered to exhibit LOH in the regions of 8 imprinted genes (H19, IGF2, KCNQ1, LIT1, GTL2, PEG1, PEG3 and NDN)." (PMID 22443985, 2012). "There was a trend for the absence of methylation at ABCB1, FOXC1, PPP2R2B, and GSTP1 in both the basal-like and normal-like tumours, while IGF2, MLH1 and PTEN were hypomethylated in the basal-like tumours but not in the normal-like tumours." (PMID 20338046, 2010). "The 12 tumours with PLAG1 mRNA expression showed higher levels of P4-specific IGF2 transcripts (P=0.01) and tended to show higher levels of P3-specific IGF2 transcripts (P=0.051) than the 8 tumours without PLAG1 expression." (PMID 19034281, 2008). "Further, we demonstrate that oHSV-D11mt infection specifically neutralized IGF2 not IGF1 within the TME, effectively abrogating the resistance conferred by IGF2/IGF1R signaling in both tumor and neutrophils/polymorphonuclear myeloid-derived suppressor cells (PMN-MDSCs)." (PMID 38853689, 2024). "IGF2 was diffusely expressed and ACTH was negative in the tumor cells." (PMID 38982409, 2024).